XBP1 (X-box binding protein 1)
Diseases named in the same sentence as XBP1 in open-access papers (continued):
Sharing a sentence is not in itself a finding about the gene and the disease.
cardiac hypertrophy (11 papers, 2011 to 2024). "Of note, vascular endothelial growth factor along with X-box binding protein 1, are known to play a significant role in autophagy, cardiac angiogenic imbalance, and progression of cardiac hypertrophy." (PMID 39224109, 2024). "Taken together, these results raise the intriguing possibility that increased expression of XBP1 actually causes accumulation of VEGF protein and myocardial angiogenesis and contribute to the progression of cardiac hypertrophy." (PMID 27133203, 2016). "The passenger strand, miR-30a-3p is also involved in autophagy and cardiac hypertrophy via targeting of X-box binding protein 1 (Xbp1), a stress response transcription factor." (PMID 27213331, 2016). "In the maladaptive phase of cardiac hypertrophy, both miR-30a* and miR-214 were increased, while XBP1 was decreased, so we treated cardiomyocyte with both miR-214 and miR-30a* mimics." (PMID 26572862, 2015). "Surprisingly, as a competent regulator of XBP1, why expression of miR-214 was enhanced while expression of XBP-1 still was increased during the early phase of cardiac hypertrophy?" (PMID 26572862, 2015). "In addition to GATA, MEF2 and NFAT families, other transcription factors, such as UBF1 86, ATF3 87, T-Cdk9 88, XBP1 89, MITF 90, HSF1 91, C/EBP 92, KLF11 93 and KLF5/BTEB2 94 have been implicated in regulating cardiac hypertrophy." (PMID 39239522, 2024). "Protein levels of the ER chaperone GRP78 and UPR transcription factor XBP1 were increased as early as 1 week and continue to rise at 2 weeks after ISO infusion, suggesting that ISO infusion caused aberrant ER stress in the early phase of cardiac hypertrophy." (PMID 27133203, 2016). "How might XBP1 expression be upregulated during the early phase of cardiac hypertrophy but downregulated in the maladaptive disease heart?" (PMID 26572862, 2015). "The probable mechanism is that ERS initiation activates IRE1, and activation of IRE1 endonuclease activity shears XBP1 to s-XBP1 and activates the JNK pathway, inducing apoptosis, which in turn leads to pathological cardiac hypertrophy." (PMID 38027018, 2023). "In isoproterenol (ISO)-induced cardiac hypertrophy mouse models, myocardial capillary density and the expression of VEGF-A were significantly decreased after sh-Xbp1 treatment." (PMID 36348288, 2022). "As cardiac expression of XBP-1 was induced in the early adaptive phase, but decreased in the maladaptive phase in hypertrophic and failing heart, it was interesting to monitor the levels of miR-30* in the different phases of AAC-induced cardiac hypertrophy." (PMID 26572862, 2015). "Furthermore, our results have indicated that XBP1 activation is required for VEGF expression in vitro and consequent angiogenesis in the early stages of hypertrophic hearts in vivo, resulting in the progression of cardiac hypertrophy." (PMID 27133203, 2016).
COVID-19 (11 papers, 2021 to 2025). A disease caused by infection with severe acute respiratory syndrome coronavirus 2. "IRE1α and XBP1 participate in the cellular response to ER stress and are activated during conditions that predispose to severe COVID-19." (PMID 37306512, 2023). "In addition to regulating ER-associated genes, XBP1 binds directly to promoters for cytokines including interleukin 6 (IL-6), which is strongly induced in severe COVID-19 and associated with the risk of respiratory failure and death (60, -, 62)." (PMID 37306512, 2023). "We found a strong and consistent increase in XBP1(S) protein in samples from patients hospitalized in the intensive care unit with acute, severe COVID-19 compared to normal controls." (PMID 37306512, 2023). "We demonstrated that pre-existing ER stress and activation of IRE1α resulted in heightened human coronavirus infection, and elevated XBP1(S) protein is present in samples from patients with severe COVID-19." (PMID 37306512, 2023). "The abundance of the protein product of spliced XBP1 in patients with COVID-19 indicates activation of this pathway also occurs during human infection." (PMID 37306512, 2023). "Plasmablasts from patients with COVID-19 expressed higher levels of XBP1 and SLAMF7 than plasmablasts from HIV-1+ patients, suggesting greater maturation." (PMID 36992700, 2023). "In this sense, an induction of markers related to ER stress, such as GRP78 and XBP1, was identified in PBMCs from COVID-19 patients compared to healthy subjects at basal levels." (PMID 35831294, 2022). "The significant elevation of XBP1 in patients with severe COVID-19 is important for the provision of additional extracellular amino acids, mitochondrial anaplerosis and cataplerosis, and subsequent sustained antibody secretion." (PMID 33936072, 2021). "To test this hypothesis, we measured the protein product of spliced XBP1 in serum from patients with severe COVID-19 and normal healthy controls using western blot." (PMID 37306512, 2023). "Considering the link between EBV replication and XBP1 activation and modulatory effects of S1R agonists in XBP1 and ER stress response, it can be proposed that fluvoxamine might have positive effects in abiding symptoms of COVID-19." (PMID 36532776, 2022). "By 6 weeks post-inclusion (T2), COVID-19 hypermethylation of genes with lowest p-value included NXN, FMNL2, ZBTB46, SLC35F3, and SHQ1, and the hypomethylated genes included ELMO1, XBP1, GRIK1, TNFAIP8, and SH3BP5." (PMID 41227320, 2025). "For example, compared to activated STAT2 and KLF5 in mild/moderate goblet cells, SPDEF, ELF3, XBP1, and NR2F6 were found activated in patients with severe COVID-19." (PMID 37936693, 2023). "Our analysis also showed that XBP1 and IRF4 are up-regulated in COVID-19 patients." (PMID 37495990, 2023). "However, XBP1, spliced protein related to IRE1 activation, was significantly reduced at basal levels in PBMCs from COVID-19 patients compared with cells from healthy subjects." (PMID 35831294, 2022). "For example, RFX2 and RFX3 showed high activity in ciliated cells regardless of disease severity, while XBP1, NR2F6, SPDEF, and ELF3 were preferentially activated in goblet cells in patients with severe COVID-19, and KLF5 and STAT2 were coactivated in patients with mild/moderate COVID-19." (PMID 37936693, 2023).
Crohn disease (11 papers, 2010 to 2024). A gastrointestinal disorder characterized by chronic inflammation involving all layers of the intestinal wall, noncaseating granulomas affecting the intestinal wall and regional lymph nodes, and transmural fibrosis. "For example, mutations in the Crohn’s Disease susceptibility genes, Atg16l1 and Xbp1 result in abnormal granule morphology and reduced numbers of granules in Paneth cells both in genetically deficient mice and in Crohn’s disease patients." (PMID 30804449, 2019). "Targeted deletion of XBP1s in murine intestinal epithelial cells results in enhanced inflammatory responses and Xbp1 polymorphisms are associated with Crohn's disease and ulcerative colitis." (PMID 23990788, 2013). "Genomewide screening could also identify X-box binding protein 1 (XBP1) as a risk factor for Crohn's disease and ulcerative colitis." (PMID 21151692, 2010). "Activation of IRE1α and XBP1 in ILC3s limited intestinal inflammation in mice and correlated with the efficacy of ustekinumab, an IL-12/IL-23 blocker, in patients with Crohn’s disease." (PMID 38949019, 2024). "Paneth cell dysfunction in both humans and mice is also associated with autophagy related 16-like 1 (ATG16L1) and X-box binding protein 1 (XBP1), both of which are associated with increased risk of Crohn's disease." (PMID 26484345, 2015). "There was concordance of gene over- (STAT1, XBP1) and underexpression (NELF, RARA) in asthma and Crohn’s disease ileum when our results were compared to another dataset (p = 3.66 × 10–7)." (PMID 34332619, 2021).
diabetic nephropathy (11 papers, 2014 to 2025). "A recent report by Zijun Liu showed that ERS initiated the progression of ferroptosis-linked EMT via the XBP1-Hrd1-Nrf2 pathway in diabetic kidney disease." (PMID 40255561, 2025). "Nuclear XBP1 is impaired in diabetic mice and in cells treated with high levels of glucose, a finding confirmed by podocyte-specific deletion of XBP1, with its deficiency promoting ER stress in diabetic nephropathy." (PMID 33558590, 2021). "Recently, it has been shown that signaling via the XBP1 branch of the unfolded protein response (UPR) is required for an adaptive ER response in diabetic nephropathy." (PMID 26545114, 2015). "A number of groups have synthesized small molecules that block IRE-1α activity and splicing of XBP-1 for use in multiple myeloma and chronic lymphocytic leukemia, however their effect on diabetic nephropathy is unpredictable." (PMID 26239352, 2015). "As evidenced in diabetic nephropathy, the pro-inflammatory cytokine TNF-α suppresses COL4A1 synthesis through the IRE1α/XBP1 endoplasmic reticulum stress pathway." (PMID 40646747, 2025). "The severity of diabetic nephropathy and levels of CHOP and ATF6 were exaggerated in podocyte-specific Xbp1-knockout mice and in transgenic mice overexpressing ATF6 in podocytes." (PMID 38778209, 2024). "In another study, ARB was found to decrease the expression of ERS markers (CHOP and XBP-1) and the activation of profibrotic growth factors, such as TGFβ, in mice with STZ-induced diabetic kidney disease." (PMID 38282657, 2024).
glioblastoma (11 papers, 2015 to 2026). The most malignant astrocytic tumor (WHO grade IV). "Together, these findings suggest that necrotic cell exposure engages the IRE1α–XBP1 axis, leading to the accumulation of XBP1u in glioblastoma cell lines." (PMID 41516347, 2026). "Previous studies have demonstrated that chronic ER stress and IRE1α–XBP1 signaling contribute to metabolic adaptation, immune modulation, and autophagy-mediated stress tolerance in glioblastoma." (PMID 41516347, 2026). "Recent data supports a role for IRE1/XBP1 in glioblastoma development and progression and as such a promising therapeutic target." (PMID 30871215, 2019). "Overexpression of this mutant in glioblastoma cells generated constitutive IRE1α autophosphorylation and splicing of XBP1 mRNA, both events being observed in basal condition and under tunicamycin treatment." (PMID 26325176, 2015). "In glioblastoma, XBP1 splicing promotes tumor stroma remodeling, angiogenesis, and invasion, whereas IRE1α‐mediated RIDD for miR‐17 displays anti‐angiogenic and antimigratory effects, suggesting a dual role of IRE1 RNase in glioblastoma aggressiveness." (PMID 32310340, 2020). "In contrast, no spliced XBP1 mRNA was detected in SNB19 glioblastoma cells." (PMID 30808679, 2019).
liver fibrosis (11 papers, 2016 to 2025). "This is related to the fact that myeloid-specific Xbp1 deficiency or pharmacological inhibition of Xbp1 ameliorates liver fibrosis in mice." (PMID 37627562, 2023). "Loss of myeloid XBP1 impairs BNIP3‐mediated mitophagy and promotes macrophage cGAS/STING/NLRP3 activation through leakage of mtDNA into the cytosol, thereby exacerbating liver fibrosis." (PMID 40211890, 2025). "On the other hand, XBP1 regulates liver fibrosis via the transport and Golgi organization-1 (TANGO1)-collagen axis and the regulation of ATG7-dependent autophagy in hepatic stellate cells." (PMID 34209019, 2021). "Further study indicated that ratios of spliced XBP1 (XBP1s) to total XBP1 (XBP1t) transcripts, an indicator of IRE1α RNase activity, were obviously elevated in CCl4-induced liver fibrosis in mice." (PMID 30538632, 2018). "XBP1 target gene signatures were significantly induced in rodent liver fibrosis models (n = 3–5) and in human samples of non-alcoholic fatty liver disease (NAFLD) (n = 72–135)." (PMID 27996033, 2016). "As a result of ancestral BPA exposure, the downregulation of hnf4a and overexpression of xbp1 and atf4 could have induced liver fibrosis and progressed the NAFLD to NASH phenotype in medaka." (PMID 38826193, 2024). "Furthermore, hepatic macrophage-specific deletion of Xbp1 in mice alleviated liver injury, which was manifested by decreased tissue inflammation, recruitment of CD11b positive macrophages, and progressive formation of hepatic fibrosis." (PMID 39113706, 2024). "However, it remains unclear whether the mechanism of independent IRE1α RNase cleaving XBP1 mRNA is involved in liver injury and liver fibrosis." (PMID 30538632, 2018). "Indicators of hepatic fibrosis, such as Col1αI and α-SMA, were significantly reduced in mice treated with FT@XBP1 compared with FFC diet-fed mice at both mRNA and protein levels." (PMID 39113706, 2024). "In addition, indicators of hepatic fibrosis, such as Col1αI and α-SMA, were significantly reduced in mice treated with FT@XBP1 compared with FFC diet-fed mice, as demonstrated by Western blot analysis." (PMID 38516345, 2023). "Likewise, recent studies also show that X-box binding protein 1 (XBP1) regulates STING signaling and the subsequent NLRP3 activation during liver fibrosis, suggesting that macrophage self-mtDNA cytosolic leakage activates cGAS/STING/NLRP3 pathway providing a novel target against liver fibrosis." (PMID 36430874, 2022). "First, both sXBP1 and uXBP1 signatures were strikingly induced in a mouse HSC-specific database of two commonly used experimental models of mouse liver fibrosis, carbon tetrachloride (CCl4) and bile duct ligation (BDL), implicating XBP1 activation in HSCs irrespective of the etiology." (PMID 27996033, 2016).
neuroblastoma (11 papers, 2012 to 2025). Neuroblastoma (NB) is the most common solid, extracranial childhood tumor. "Studies using parkin and its pathogenic mutants in SH-SY5Y neuroblastoma cells identified the protective role of the IRE1α/XBP1 signaling axis against NO-induced apoptosis." (PMID 41473415, 2025). "For both the JEV and the DV, IRE1-XBP1 branch activation is associated with cell survival as evidenced by the fact that the knockdown of XBP1 brings along an enhanced cytopathic effect in a mice neuroblastoma cell line." (PMID 36192392, 2022). "We have induced ER stress in SH-SY5Y neuroblastoma cells with tunicamycin treatment for 2 and 8 h and validated it by quantifying XBP1 splicing." (PMID 34206832, 2021). "Therefore, we investigated the relationship among ERVW-1, ATF6, and XBP1 with cytological experiments using the neuroblastoma cell line SH-SY5Y." (PMID 37376599, 2023). "Various studies also enlighten the effect of rotenone on the induction of ER stress via the upregulation of XBP-1 and activation of CHOP in neuroblastoma cells." (PMID 37529115, 2023). "ER stress (tunicamycin) activated three branches of the UPR; the PERK, IRE1α, and ATF6 branches, as indicated by the induction of CHOP transcription, XBP1 splicing, and HERP expression, respectively, in the SH-SY5Y neuroblastoma cell line." (PMID 24421337, 2014). "To test the ability of α-Syn to induce XBP1 activation, we treated SY5Y human neuroblastoma cells with 2 μM of monomeric, oligomeric, and fibrillar forms of α-Syn for 8 h." (PMID 22528838, 2012).
Parkinson disease (11 papers, 2014 to 2025). A progressive degenerative disorder of the central nervous system characterized by loss of dopamine producing neurons in the substantia nigra and the presence of Lewy bodies in the substantia nigra and locus coeruleus. "The XBP1-TagRFP sensor for ER stress associated with the IRE1 pathway was used in a recent study to detect the development of ER stress in transgenic iPSC lines derived from Parkinson’s disease patients." (PMID 41009497, 2025). "(2019) MicroRNA-326 suppresses iNOS expression and promotes autophagy of dopaminergic neurons through the JNK signaling by targeting XBP1 in a mouse model of Parkinson's disease." (PMID 38767306, 2024). "Recent studies on Parkinson's disease have shown that RTCB-1 can play a neuroprotective effect by splicing XBP-1 mRNA." (PMID 35721061, 2022). "According to neurodegenerative diseases, it was shown that overexpression of XBP1 may be neuroprotective in the animal models of Parkinson’s disease, while its silencing leads to a decreasing in neuron loss in mice models of HD." (PMID 41009497, 2025). "Enhancement of XBP1 was shown to protect against Parkinson’s disease." (PMID 38311171, 2024). "We were unable to identify the spliced form of XBP1 in samples of iPSC and DA neurons cultured under normal conditions, although it has been shown that this pathway can be turned on in patients with Parkinson’s disease." (PMID 38672099, 2024). "In summary, we hypothesize that the overexpression of miR-34a-5p in affected brain regions of Alzheimer’s and Parkinson’s disease patients could contribute to neurodegeneration by targeting IRE1α and XBP1." (PMID 32531952, 2020).
steatosis (11 papers, 2012 to 2025). Increased lipid within the cytoplasm of cells. "In addition, chronic liver ER stress was observed in the steatosis of mice strains with genetically deficient in leptin as well as genetically modified IRE1/XBP1, PERK/eIF2α and ATF6 signaling pathways." (PMID 32121602, 2020). "An overall favorable effect on steatohepatitis-related parameters was noted in the FT@XBP1 group, including a decrease in steatosis percentage, intrahepatic ballooning, and lobular inflammation, which improved liver histology." (PMID 39113706, 2024). "All three ER stress-sensing pathways (ATF6α, PERK/eukaryotic translation initiation factor 2α (eIF2α), and IRE1α/X box binding protein 1 (XBP1)) can regulate the development of steatosis in the liver." (PMID 35873545, 2022). "Of particular interest, in a human study, there is a 2-fold increase in XBP1s′ mRNA levels in the liver of obese patients with steatosis, and obese patients with fatty liver have elevated liver XBP1 protein levels." (PMID 35863429, 2022). "We found that XBP1 deficiency largely attenuated FFC diet-induced liver injury and steatohepatitis-related parameters in mice, for example intrahepatic ballooning and steatosis percentage, which relieved lipid accumulation and improved liver histology." (PMID 38516345, 2023). "This may in part explain why absence of hepatic IRE1α led to increased lipid accumulation, while deficiency in its downstream target XBP1 did not affect steatosis." (PMID 22195283, 2012). "The FFC diet significantly increased NAS compared with the CD diet, whereas FT@XBP1 treatment remarkably reduced NAS compared with mice fed with an FFC diet, as demonstrated by evidently reduced lobular inflammation and steatosis." (PMID 38516345, 2023). "The FFC diet significantly increased NAFLD scores (NAS > 5) compared with CD, whereas FT@XBP1 treatment remarkably reduced NAS compared with mice fed with an FFC diet or treated with FT@NC (P = 0.003), as demonstrated by evident reduced lobular inflammation and steatosis." (PMID 39113706, 2024).